ARG1 (arginase 1)
Diseases named in the same sentence as ARG1 in open-access papers (continued):
Sharing a sentence is not in itself a finding about the gene and the disease.
lung fibrosis (continued). "Importantly, we found that lung fibrosis was markedly decreased and body weight recovery improved with ARG1 inhibition." (PMID 40875483, 2025). "Finally, taking a genetic approach with macrophage-specific Arg1-KO mice in which Cre-mediated deletion efficiency was approximately 55%, we found that lung fibrosis was decreased after injury in KO mice compared with control mice." (PMID 40875483, 2025). "Macrophages release pro-fibrotic cytokines TGF-β and Arg-1, which act on fibroblasts and pericytes in the lung, promoting myofibroblast formation and extracellular matrix deposition, leading to the aggravation of pulmonary fibrosis." (PMID 39723218, 2024). "Bleomycin-induced pulmonary fibrosis in mice revealed significant upregulation of ARG-1." (PMID 37580758, 2023). "Conversely, the down-regulation of ARG-1 in mice attenuated pulmonary fibrosis." (PMID 37580758, 2023). "In addition, in pulmonary fibrosis, iNOS and Arg1 are regarded as being in a competitive relationship for arginine, and Arg1 is upregulated in M2 macrophages localized in fibrotic lesions." (PMID 37180123, 2023). "Regarding the urea cycle, pirfenidone, an ARG1 inhibitor, has shown positive results in patients with idiopathic pulmonary fibrosis, and therefore inhibition of ARG1 might be a valuable therapeutic aim in SSc." (PMID 35327409, 2022). "Increased Arg-1 suggests an aggravation of catabolic activity but may also have implications for lung fibrosis and airway resistance." (PMID 34367144, 2021). "The overall tissue expression of Arg-1 in the SA wall suggests increased catabolic activity, a sign of cellular senescence but could also have implication for in lung fibrosis and airway resistance." (PMID 29042607, 2017). "In this study, LPS/IL-4-induced macrophages showed upregulation of Arg1 compared to M2 macrophages, despite expression of iNOS being very low, suggesting that both M2 and LPS/IL-4-induced macrophages may be involved in the pathogenesis of pulmonary fibrosis." (PMID 37180123, 2023). "ARG1 could regulate the macrophage phenotype transition and Akt1-mediated mitophagy contributed to alveolar macrophage apoptosis resistance and was required for pulmonary fibrosis development." (PMID 31105564, 2019). "Small-molecule ARG1 inhibition suppressed both ornithine levels and collagen expression in cultured, precision-cut IPF lung slices and in murine lung fibrosis." (PMID 40875483, 2025). "In both murine lung fibrosis and cultured, precision-cut IPF lung slices, ARG1 inhibition decreased collagen expression." (PMID 40875483, 2025). "We observed elevated levels of CD206, MGL1/2, Arg-1, and Ym1 genes and proteins in the lung tissue in mice with BLM-induced pulmonary fibrosis, in agreement with previously reported findings." (PMID 38259493, 2023). "In summary, our data imply that an increased MSR1, IL-13, and Arg1 expression occurs in patients with IPF, an observation that could suggest a possible role for M2 macrophages in the pathogenesis of pulmonary fibrosis." (PMID 33604393, 2021). "However, Arg1 is not selected as a differentially expressed gene in SSc-Related Progressive Lung Fibrosis in humans." (PMID 26444860, 2015).
endothelial dysfunction (31 papers, 2013 to 2026). In vascular diseases, endothelial dysfunction is a systemic pathological state of the endothelium (the inner lining of blood vessels) and can be broadly defined as an imbalance between vasodilating and vasoconstricting substances produced by (or acting on) the endothelium. "There are multiple studies showing increased Arg1 activity/protein levels in serum of humans with myocardial infarction, and they were linked to endothelial dysfunction via decrease of l-arginine bioavailability." (PMID 39952693, 2025). "Serum exosomes from diabetic db/db mice were ingested by normal mouse aortic endothelial cells, and severe endothelial dysfunction occurred, which was caused by the transfer of arginase-1 (arginase 1) by serum exosomes to endothelial cells." (PMID 36818396, 2023). "The effect of ARG1 gene polymorphism through endothelial dysfunction has been previously proposed in the studies involving cardiovascular diseases." (PMID 34830689, 2021). "Endothelial dysfunction/NO bioavailability is associated with worse plasma leakage, occurs early in dengue illness and correlates with hypoargininemia and high arginase-1 levels." (PMID 28673038, 2017). "The findings could have been due to the fact that traumatic brain injury also causes endothelial dysfunction in the systemic microcirculation through arginase-1–dependent uncoupling of endothelial nitric oxide synthase." (PMID 34917416, 2021). "Moreover, ARG1 mRNA levels are reported to be positively associated with the up-regulation of soluble intercellular adhesion molecule-1, which is a circulating biomarker for endothelial dysfunction." (PMID 24763700, 2014). "The conclusion that the transfer of arginase-1 protein by the EVs to the endothelial cells is of functional importance is supported by the finding that T2D RBC-EVs induced endothelial dysfunction in aortas from endothelial cell arginase-1–KO mice." (PMID 40111409, 2025). "The study demonstrates that EVs produced by RBCs from patients with T2D induce endothelial dysfunction through a mechanism involving increased uptake of EVs in endothelial cells, delivery of arginase-1, and induction of vascular oxidative stress." (PMID 40111409, 2025). "To further elucidate the role of arginase-1 carried by the EVs in the development of endothelial dysfunction, we coincubated mouse aortic rings with T2D RBC-EVs in the presence or absence of the arginase inhibitor 2(S)-amino-6-boronohexanoic acid (ABH)." (PMID 40111409, 2025). "EVs derived from T2D-RBCs induce endothelial dysfunction through upregulated arginase-1 and increased oxidative stress in vasculature." (PMID 40111409, 2025). "We demonstrate that the EVs secreted by T2D-RBCs are taken up by endothelial cells to a greater extent in comparison with H RBC-EVs and induce endothelial dysfunction via the transfer of arginase-1 by the EVs and increased vascular oxidative stress." (PMID 40111409, 2025). "Collectively, these observations suggest that T2D RBC-EVs increase vascular arginase-1 and oxidative stress, leading to endothelial dysfunction." (PMID 40111409, 2025). "Our group has shown that upregulated arginase-1 in RBCs is a key factor contributing to the development of endothelial dysfunction in T2D." (PMID 40111409, 2025). "RBCs derived from T2D patients induce endothelial dysfunction via upregulation of arginase-1 and oxidative stress in the target vessel." (PMID 40111409, 2025). "By using a translational approach, we aimed to demonstrate that RBC-derived EVs are important mediators of endothelial dysfunction in T2D through the upregulation of arginase-1 and increased ROS formation." (PMID 40111409, 2025). "It is concluded that T2D-RBCs induce endothelial dysfunction through increased uptake of EVs that transfer arginase-1 from RBCs to the endothelium to induce oxidative stress and endothelial dysfunction." (PMID 40111409, 2025).
endothelial dysfunction (continued). "FH‐RBCs induce endothelial dysfunction dependent on LDL‐c levels via arginase 1 and ROS‐dependent mechanisms." (PMID 36324273, 2023). "We have previously shown that red blood cells (RBCs) from patients with type 2 diabetes induce endothelial dysfunction through increased arginase 1 and reactive oxygen species (ROS)." (PMID 36324273, 2023). "Accordingly, we provide evidence that FH‐RBCs and high LDL‐c levels upregulate arginase 1 in the vasculature and consequently induce endothelial dysfunction." (PMID 36324273, 2023). "Studies have also shown that hepatic EVs deliver Arg-1 to endothelial cells and thus enhances endothelial dysfunction." (PMID 35850658, 2022). "Elevated ARG1 in serum exosomes of diabetic mice can be delivered to ECs, which subsequently results in diabetic endothelial dysfunction via inhibiting NO synthesis." (PMID 36209203, 2022). "Increased arginase-1 activity in the RBCs of patients with Type 2 diabetes is associated with superoxide production and accelerated endothelial dysfunction, suggesting a link between increased RBC arginase-1 activity and CVD." (PMID 33192610, 2020). "Moreover, the endothelial dysfunction induced by T2D RBC-EVs in aortas from endothelial cell arginase-1–KO mice was attenuated by the arginase inhibitor ABH." (PMID 40111409, 2025). "Since our group previously discovered that T2D-RBCs induce endothelial dysfunction via upregulation of arginase-1 and increased formation of ROS, we hypothesized that arginase-1 and ROS are key players in the endothelial dysfunction triggered by T2D RBC-EVs." (PMID 40111409, 2025). "In addition, the first evidence that Arg1 present in RBCs can modulate endothelial dysfunction and the outcome of I/R injury has come from bioassays." (PMID 39952693, 2025). "EVs derived from T2D-RBCs carrying arginase-1 induce endothelial dysfunction." (PMID 40111409, 2025). "We, therefore, hypothesized that the EVs derived from T2D-RBCs carry arginase-1, leading to endothelial dysfunction." (PMID 40111409, 2025). "Indeed, we demonstrate that the EVs contain arginase-1, and pharmacological inhibition of arginase prevented the development of endothelial dysfunction." (PMID 40111409, 2025). "Similarly, co-incubation of eNOS KO RBCs with endothelial-specific Arg1 KO vessels prevented the observed endothelial dysfunction." (PMID 36681048, 2023). "Moreover, vessels from endothelial cell-specific arginase 1 KO mice were resistant to eNOS KO-RBC-induced endothelial dysfunction." (PMID 36681048, 2023). "Further, in the context of cardiovascular disease (CVD), RBC imbalances in arginase and NO synthase suggest that increased RBC arginase-1 activity decreases NO bioavailability, superoxide production, endothelial dysfunction, and enhances post-ischemic cardiac failure." (PMID 33192610, 2020). "Although ARG1+ M2 macrophages contribute to resolve arthritis inflammation in mice, ARG1 activity may be responsible for subclinical endothelial dysfunction also in RA patients." (PMID 31354721, 2019). "Our earlier study indicated that SAA enhances arginase (Arg)-1/2 expression in cultured endothelial cells and may potentially impact on NO bioavailability, promoting endothelial dysfunction; Arg-1/2 metabolizes L-arginine to yield urea and L-ornithine." (PMID 30899260, 2019). "Both ARG1 and ARG2 are found in endothelium and have been implicated in endothelial dysfunction." (PMID 29890043, 2018). "Endothelial dysfunction correlates with lower plasma l-arginine and higher arginase-1 levels." (PMID 28673038, 2017). "Our finding suggests a central role for arginase 1 in Ang II-induced endothelial dysfunction." (PMID 25807386, 2015). "In addition, the finding that incubation with the EVs from T2D-RBCs was associated with increased expression of arginase-1 in the vessel wall of both mouse aorta and human IMA suggests that the EVs induced endothelial dysfunction via delivery or upregulation of arginase-1 in the endothelium." (PMID 40111409, 2025).
endothelial dysfunction (continued). "However, ARG1 also could induce endothelial dysfunction and promote the progress of atherosclerosis by competing with nitric oxide synthase (NOS) for the common substrate-L-arginine and inhibited of biosynthesis of nitric oxide (NO)." (PMID 33603775, 2021). "ARG1 expression and activity can be upregulated in RBCs from T2DM by a ROS-dependent mechanism, which leads to endothelial dysfunction in healthy arteries following co-incubation of T2DM RBCs and healthy arteries." (PMID 36209203, 2022). "Using a gene deletion model, we investigated involvement of arginase isoforms arginase 1 and 2 (ARG1 and ARG2) in hypertension and endothelial dysfunction in a mineralocorticoid-salt mouse model." (PMID 23908657, 2013). "Endothelial dysfunction as a surrogate for NO bioavailability correlated with lower l-arginine and higher arginase-1 levels, but not ADMA, suggesting that hypoargininemia resulting from high arginase-1 levels plays a role." (PMID 28673038, 2017).
pancreatic cancer (31 papers, 2013 to 2025). "Immunosuppressive macrophages are classically defined by the expression of the enzyme Arginase 1 (ARG1), which we demonstrated is potently expressed in pancreatic tumor-associated macrophages from both human patients and mouse models." (PMID 36727849, 2023). "To explore whether circulating ARG1 levels are associated with cachexia in patients, we measured ARG1 protein levels in plasma from gastrointestinal and pancreatic cancer patients, two groups at high risk of developing cachexia." (PMID 40474277, 2025). "PI3K-γ expression in myeloid cells in murine pancreatic cancer models is associated with transcription of genes associated with the M2-macrophage phenotype in pancreatic cancer, including immunosuppressive factors like Arg1, TGF-beta, and IL-10." (PMID 34512641, 2021). "Our data demonstrate that Arg1 drives immune suppression in pancreatic cancer by depleting arginine and inhibiting T cell activation." (PMID 36727849, 2023). "To investigate this metabolic function, we used a genetic and a pharmacologic approach to target Arg1 in pancreatic cancer." (PMID 36727849, 2023). "Genetic inactivation of Arg1 in macrophages, using a dual recombinase genetically engineered mouse model of pancreatic cancer, delayed formation of invasive disease, while increasing CD8+ T cell infiltration." (PMID 36727849, 2023). "This was also supported by our findings that at least three positive correlations between ARG1 and immune checkpoints in colon, breast, lung, and pancreatic cancers were observed." (PMID 38012650, 2023). "To validate the deletion of Arg1 in macrophages, we harvested bone marrow (BM) cells from wild type (WT) or Lyz2Cre/+;Arg1f/f mice and cultured these directly in pancreatic cancer cell conditioned media (CM) for 6 d." (PMID 36727849, 2023). "Our findings show that one of the mechanisms by which myeloid cells promote immune suppression and tumor growth in pancreatic cancer is through overexpression and activity of Arg1." (PMID 36727849, 2023). "We are unable to provide sufficient data supporting ARG1 expression in human pancreatic tumors as it experiences high rates of drop-out during scRNA-seq." (PMID 35156921, 2022). "We have recently found that either arginine depletion or neutrophil-released arginase-1 highly potentiates the antitumor action of the ER-targeting antitumor ether lipid edelfosine against pancreatic cancer cells, opening up new avenues for cancer treatment." (PMID 34439330, 2021). "Neutrophil-released arginase-1 and arginine deprivation potentiated the antitumor action against pancreatic cancer cells of the ER-targeted antitumor alkylphospholipid analog edelfosine." (PMID 34131176, 2021). "Combination with neutrophil-released arginase-1 clearly potentiates the antitumor activity of edelfosine against pancreatic cancer cells." (PMID 34439330, 2021). "Especially CD11b has been associated with recruitment of myeloid cells with an immunosuppressive phenotype (CD206, ARG1) in human pancreatic tumor analyses." (PMID 34084172, 2021). "Taken together, these results strongly indicate PMN-Spt induces apoptosis in pancreatic cancer cells mainly through an arginase-1-dependent L-Arg depletion and subsequent PERK-driven ER stress." (PMID 34131176, 2021). "In line with our previous study in pancreatic cancer patients, GMCs expressed significantly higher levels of ARG1 than MMCs." (PMID 28008330, 2016). "Next, to determine whether the increase in Arg1 expression was recapitulated in a mouse model of pancreatic cancer, we analyzed our mouse sc-RNA-seq data from healthy mice and tumor-bearing KPC (KrasLSL-G12D/+;p53LSL-R172H/+;Ptf1aCre/+) mice." (PMID 36727849, 2023). "Thus, both in mouse and human pancreatic cancer, ARG1 is highly expressed and largely confined to tumors, where it is predominantly expressed in macrophages." (PMID 36727849, 2023). "In pancreatic cancer, Dectin-1+ TAMs can regulate the expression of Arg1 by binding to galectin-9." (PMID 37422529, 2023).
pancreatic cancer (continued). "Thus, we conclude that myeloid cells are the main source of ARG1 in the pancreatic cancer microenvironment." (PMID 36727849, 2023). "Based on a publicly available human PDA microarray data set (GSE71729), we found that high ARG1 expression in pancreatic cancer correlated with worse survival, suggesting that ARG1 in myeloid cells may play a functional role in human PDA." (PMID 36727849, 2023). "Interestingly, pancreatic cancer BxPC-3 cells were very sensitive to the action of arginase-1, either as a recombinant enzyme or from neutrophil sonicates." (PMID 34131176, 2021). "We have very recently found that the release of arginase-1 from neutrophils could promote an ER-stress-mediated cell death process in pancreatic cancer cells." (PMID 34439330, 2021). "Moreover, other NSAIDs, e.g., diclofenac, have been shown to increase protein expression and the activity of arginase 1, which, however, translated into the inhibited growth of xenografted pancreatic tumors." (PMID 32932854, 2020). "Pancreatic cancer-derived EV could downregulate HLA-DR, induce arginase-1 (Arg-1) expression, increase production of reactive oxygen species (ROS) and the levels of phosphorylated STAT1 and STAT3 in monocytes." (PMID 32878277, 2020). "The specific dependency of PDA on ARG2 rather than the principal hepatic enzyme ARG1 opens a therapeutic window for obesity-associated pancreatic cancer." (PMID 28808255, 2017). "In pancreatic cancer samples tested by the International Cancer Genome Consortium, only 1% contained ARG1 mutations, and no ARG2 mutations were seen." (PMID 28098776, 2017). "This confirms that ARG1 expression is characteristic for granulocytic MDSCs in pancreatic cancer." (PMID 24741628, 2014). "Empirical data has evidenced that the strategic inhibition of targets such as Pin1, MEK, STAT3, ARG1 can significantly elevate the response rates of pancreatic neoplasms to anti-PD1 therapy, enable more pancreatic cancer patients to benefit from immunotherapy." (PMID 40433359, 2025). "A reduction in tumor-promoting macrophage markers such as Arginase 1 (Arg 1) and CCL2 was also observed in BMDMs stimulated with conditioned media from pancreatic cancer cells and treated with I-BET-762." (PMID 39337472, 2024). "In pancreatic tumors, TAMs exhibit both M1 and M2 phenotypes, but show preferential expression of M2 markers such as Arginase 1, CD206, and TGF-β leading to a higher M2:M1 ratios which correlates with a poorer prognosis in pancreatic cancer patients." (PMID 36333531, 2022). "EV-miR-301a from hypoxic pancreatic cancer cells induces the M2 polarization of macrophages by targeting PTEN, which in turn promotes the migration, invasion, EMT and lung metastasis of pancreatic cancer cells probably by secreting IL10, TGF-β and arginase-1." (PMID 32503543, 2020). "We also detected representative markers of THP-1 macrophages (CD163/Arg-1/IFN-γ/iNOS) induced by the pancreatic cancer cells at the mRNA and protein levels, according to the characteristics of TAMs." (PMID 31685825, 2019). "Similarly, treatment with EGFR inhibitor targeted therapy suppresses MDSCs and Arg1 expression, resulting in heightened levels of Th1 cytokines such as IL-12 and tumor necrosis factor-alpha (TNF-α) and reduced pancreatic cancer." (PMID 38464388, 2024). "However, we note expression of the strongly Arg1-correlated gene, PIK3CD, in macrophage populations in human pancreatic tumors." (PMID 35156921, 2022). "Importantly, because ARG1 and not ARG2 is the main hepatic ureagenic enzyme in mammals, specific targeting of ARG2 may provide a therapeutic opportunity for the treatment of pancreatic cancer patients, particularly those suffering from obesity and the metabolic syndrome." (PMID 28808255, 2017).